USP17L21 (ubiquitin specific peptidase 17 like family member 21)
Description:
Deubiquitinating enzyme that removes conjugated ubiquitin from specific proteins to regulate different cellular processes that may include cell proliferation, progression through the cell cycle, apoptosis, cell migration, and the cellular response to viral infection.
Tractability: No criterion of Open Targets' tractability assessment is met for any kind of drug.
Gene: Protein-coding gene on chromosome 4 (9,262,872 to 9,264,464, forward strand). Ensembl gene ENSG00000249811.
Subcellular location: Nucleus; Endoplasmic reticulum
Pathways (Reactome):
Metabolism of proteins: Ub-specific processing proteases
Gene Ontology:
Molecular function: cysteine-type deubiquitinase activity
Biological process: regulation of apoptotic process; protein deubiquitination
Cellular component: endoplasmic reticulum; nucleus
Homologues: Paralogues in human: USP17L12 (99% identical), USP17L20 (99% identical), USP17L24 (99% identical), USP17L25 (99% identical), USP17L26 (99% identical), USP17L27 (99% identical), USP17L28 (99% identical), USP17L29 (99% identical), USP17L30 (99% identical), USP17L11 (99% identical), USP17L17 (99% identical), USP17L19 (99% identical), and 59 more.